CETP (cholesteryl ester transfer protein)
Diseases named in the same sentence as CETP in open-access papers (continued):
Sharing a sentence is not in itself a finding about the gene and the disease.
thyroid (6 papers, 2015 to 2020). "Thyroid hormones can influence HDL metabolism by increasing CETP activity, which exchanges cholesteryl esters from HDL2 to the VLDL and from TGs to HDLs." (PMID 32549042, 2020). "Thyroid hormones can also influence HDL metabolism by increasing cholesteryl ester transfer protein activity." (PMID 28451029, 2017). "Moreover, thyroid hormones also increase the activity of CETP and trigger the exchange of HDL to VLDL." (PMID 32549042, 2020). "Studies have also indicated that thyroid hormones may affect HDL metabolism by increasing the cholesteryl ester transfer protein activity and that they may also stimulate lipoprotein lipase." (PMID 28008862, 2017).
hypoalphalipoproteinemia (5 papers, 2012 to 2024). A metabolic disorder characterized by deficiency of high density (alpha) lipoprotein in the blood. "Based on our data and those of others, it seems reasonable to believe that most of the 15 secreted CETP missense variants in Class C do not cause autosomal dominant hyperalphalipoproteinemia or hypoalphalipoproteinemia." (PMID 38039300, 2023).
psoriasis (5 papers, 2015 to 2023). An autoimmune condition characterized by red, well-delineated plaques with silvery scales that are usually on the extensor surfaces and scalp. "SORT and CETP may perhaps serve as such markers considering their role in metabolic disorders, which are undoubtedly associated with psoriasis." (PMID 35448527, 2022). "Previous studies have shown that CETP is decreased in some patients with psoriasis and increased in others." (PMID 35982498, 2022). "Both are the best models for studying the relationship between lower HDL and psoriasis, so CETP-Tg and PLTP-Tg mice with low HDL were selected as the subjects." (PMID 35982498, 2022). "Then, we searched for studies that evaluated serum CETP concentrations in psoriasis patients." (PMID 37234169, 2023). "implied that CETP could aggravate psoriasis, and this could be CETP’s role in regulating inflammation and blood lipids." (PMID 37234169, 2023). "CETP is regarded as a marker of liver side effects of acitretin treatment in psoriasis." (PMID 35982498, 2022). "Furthermore, CETP seems to exert a protective role in these disorders development in psoriasis." (PMID 35448527, 2022). "Compared with other studies, the novelty of the present study is that both CETP and PLTP, the key proteins for lipid transfer and lipoprotein metabolism, affect pathological alterations in psoriasis." (PMID 35982498, 2022). "We are one of the first to report on possible role of CETP and SORT serum concentration in the management of psoriasis." (PMID 35448527, 2022). "This study discovers that increased CETP and PLTP aggravates psoriasis in an imiquimod-induced mouse model." (PMID 35982498, 2022). "Elevated CETP and PLTP aggravate psoriasis in a imiquimod-induced mouse model." (PMID 35982498, 2022). "This study examined whether elevated CETP and PLTP could aggravate psoriasis in a psoriasis vulgaris mouse model." (PMID 35982498, 2022). "We did not observe any correlation between the psoriasis severity and CETP concentration, but we managed to find a positive correlation with age." (PMID 35448527, 2022). "The present study demonstrated that elevated expression of CETP and PLTP could aggravate the clinical and pathohistological characteristics and inflammation in mice with psoriasis." (PMID 35982498, 2022). "The present study found that increased CETP could aggravate psoriasis, suggesting that nonlipid transfer properties of CETP and confounders or modifiers may take part in that interplay." (PMID 35982498, 2022). "The role of CETP is still not completely clear because it is suspected that it may also have other nonlipid transfer properties, so its true role in psoriasis is yet to be discovered and may be much more complex." (PMID 35448527, 2022). "Therefore, whether CETP and PLTP affect psoriasis was observed in imiquimod-induced mouse models." (PMID 35982498, 2022).
steatosis (5 papers, 2014 to 2023). Increased lipid within the cytoplasm of cells. "In addition, we observed in the E3L.CETP mice a profound improvement in steatosis and hepatic inflammation, while precluding fibrosis development when treatment was started." (PMID 33658534, 2021).
coronary artery stenosis (4 papers, 2011 to 2024). "Our previous study reported that the I405V polymorphism of CETP gene was linked with severity of coronary artery stenosis estimated by the Gensini Score (defines narrowing or occlusion of the lumen of the coronary arteries from 1 to 32 score; the LM has the highest location score)." (PMID 21899732, 2011). "From our Korean cohort, the CETP rs2303790 SNP was significantly associated with HDL-C variability, but not with the risk of CACS ≥400 nor coronary stenosis ≥70%." (PMID 35174233, 2022).
hyperalphalipoproteinemia 1 (4 papers, 2012 to 2025). "CETP: Genetic loss-of-function CETP variants cause hyperalphalipoproteinemia 1, which is inherited in an autosomal co-dominant manner." (PMID 40004987, 2025). "Mutations in the CETP gene frequently cause familial hyperalphalipoproteinemia; most CETP polymorphisms, such as three common CETP genotypes Taq1B (+279G>A), Ile405Val (+16A>G) and −629C>A, are equally associated with elevated HDL-C levels." (PMID 23189141, 2012). "The development of hyperalphalipoproteinemia 1, a monogenic condition with autosomal dominant inheritance, has been linked to pathogenic variants in the CETP gene, highlighting the crucial function of CETP in high-density lipoprotein metabolism." (PMID 37569628, 2023).
intracerebral hemorrhage (4 papers, 2016 to 2024). A cerebrovascular disorder characterized by bleeding into one or both cerebral hemispheres including the basal ganglia and the cerebral cortex. "Another study showed that variation in CETP associated with higher HDL-C is also associated with an increased risk of intracerebral hemorrhage." (PMID 30422133, 2018).
liver fibrosis (4 papers, 2019 to 2024). "Another possible explanation is that liver fibrosis associated with S. japonicum infection may influence the activity of cholesteryl ester transfer protein (CETP), and thus lead to reduced reverse cholesterol transport, which results in lower HDL clearance." (PMID 35906693, 2022). "Previously, we showed that progression of liver fibrosis correlated with plasma pro‐inflammatory cytokine levels and gene expression in the liver livers of ApoE*3‐Leiden.CETP mice." (PMID 34505423, 2021). "Consistent with this view, when cholesterol is supplied to HFD diet, E3L mice develop NASH and liver fibrosis as well, and E3L and E3L.CETP mice have been shown to be established diet-induced NASH and liver fibrosis models." (PMID 30949516, 2019).
type 1 diabetes (4 papers, 2014 to 2026). "Increased CETP activity was noted in individuals with type 1 diabetes, resulting in peripheral hyperinsulinaemia." (PMID 37537394, 2023). "The activities of the HDL-associated enzymes PLTP (p < 0.001), and CETP (p = 0.007) were higher and paraoxonase (PON-1) activity, an anti-oxidative enzyme bound to HDL, decreased in patients with type 1 diabetes (p = 0.027)." (PMID 24959195, 2014). "This first multi-method characterization study of sdLDL in type 1 diabetes highlights the contribution of ApoC3, CETP and HL to sdLDL-C enrichment and suggests that direct assessment of sdLDL may improve cardiovascular risk stratification." (PMID 42022901, 2026).
unstable angina (4 papers, 2012 to 2024). "On the other hand, CETP inhibitors besides failing to demonstrate any benefit were associated with increased incidence of hospitalization due to unstable angina." (PMID 24728455, 2014). "Low CETP levels, proxied by HDL-C, were associated with a decreased risk of CHD, angina, HF, intracerebral and subarachnoid haemorrhage in Europeans." (PMID 38906890, 2024).
autoimmune disease (3 papers, 2014 to 2019). A disorder resulting from loss of function or tissue destruction of an organ or multiple organs, arising from humoral or cellular immune responses of the individual to their own tissue constituents. "Because of higher CETP activity, low HDL-C levels and prevalent dysfunctional HDL become risk factors for autoimmune disease with inflammation and other risk factors." (PMID 31772618, 2019). "Especially in an autoimmune disease state, such as rheumatoid arthritis, arterial stiffness was shown to be positively correlated with elevation of CETP activity." (PMID 29854085, 2018).
cognitive decline (3 papers, 2022 to 2025). "The Cache County study found that the V allele of the rs5882 (I405V) CETP polymorphism was associated with reduced cognitive decline determined by the Modified Mini-Mental State Examination (3MS) in 4486 subjects who were followed longitudinally for 12 years." (PMID 37974180, 2023). "For example, CETP and APOE facilitate cholesterol metabolism, and function in shared pathways of late‐onset AD and cognitive decline during aging." (PMID 40665476, 2025).
Cognitive impairment (3 papers, 2017 to 2025). Abnormal cognition is characterized by deficits in thinking, reasoning, or remembering. "Additionally, we found that lipid metabolism-associated DEPs, including ApoC-II, Apo(a), cholesteryl ester transfer protein (CETP), and LPL, were significantly altered in the TBI patients with cognitive impairment." (PMID 28251161, 2017). "ApoC-II and CETP were upregulated in the TBI patients with cognitive impairment." (PMID 28251161, 2017).
Hyperinsulinemia (3 papers, 2017 to 2024). An increased concentration of insulin in the blood. "A series of recent studies have indicated that plasma CETP activity decreased by hyperinsulinemia condition in healthy subjects, but not in diabetic patients." (PMID 34354158, 2021).
hyperlipoproteinemia (3 papers, 2015 to 2025). An elevated concentration of lipoproteins. "Pharmacological inhibition of CETP has been attempted in the past decade, and has demonstrated very positive results in a rabbit model of diet-induced hyperlipoproteinemia." (PMID 25849946, 2015). "Furthermore, statins decrease plasma cholesteryl ester transfer protein (CETP) activity in both normolipidemic individuals and patients with hyperlipoproteinemia, raising HDL-cholesterol and reducing triglycerides." (PMID 40239868, 2025).
hyperthyroidism (3 papers, 2021 to 2025). Overactivity of the thyroid gland resulting in overproduction of thyroid hormone and increased metabolic rate. "Cholesteryl ester transfer protein (CETP) in plasma is increased in patients with hyperthyroidism and decreased in those with reduced thyroid function compared." (PMID 38523861, 2021). "Since CETP and hepatic lipase activity are increased in hyperthyroidism, HDL levels are lower." (PMID 40937266, 2025). "Additionally, other studies have shown a decrease in HDL levels in patients with hyperthyroidism due to increased cholesteryl ester transfer protein-mediated transfer of cholesteryl esters from HDL to very-low-density lipoproteins and increased catabolism of HDL." (PMID 37627914, 2023).
lipid metabolism disorder (3 papers, 2014 to 2024). "Diseases such as hyperalphalipoproteinemia 1 and lipid metabolism disorder are associated with CETP." (PMID 39050255, 2024). "The TaqI B (rs708272) single-nucleotide variant, i.e., the +279 G/A substitution in intron 1 of the CETP gene, is actively investigated as a risk factor of lipid metabolism disorders." (PMID 31739638, 2019).
liposarcoma (3 papers, 2016 to 2021). A usually painless malignant tumor that arises from adipose tissue. "In vitro work supports a role for intracellular CETP in regulating TG metabolism and LDL uptake in adipocytes and liposarcoma cells." (PMID 33625789, 2021). "In addition, Izem and Morton (2007) have shown that CETP expression modulates cholesterol and triglyceride homeostasis in the SW872 human liposarcoma cell line." (PMID 33430172, 2021).
liver diseases (3 papers, 2010 to 2024). "Although reduced LCAT activity is common in a variety of liver diseases, the current report is, to the best of our knowledge, the first to identify increased CETP and PLTP activities as being associated with chronic liver impairment." (PMID 20470383, 2010). "Since SH42 protects against the development of metabolic disease-associated steatotic liver diseases on a high-fat high-cholesterol diet, we evaluated whether SH42 also reduces lipid accumulation in the livers of Western-type diet-fed E3L.CETP mice." (PMID 38770137, 2024). "For example, patients with severe liver disease have lower circulating LCAT, cholesteryl ester transfer protein (CETP) and higher HL than healthy subjects, raising the possibility that defective lipoprotein remodeling and catabolism may account for the appearance of LP-Z." (PMID 32927635, 2020).
small vessel stroke (3 papers, 2024). "While we did not have access to genetic data on vascular dementia (VD), we were able to show that decreased plasma concentrations of CETP protect against small vessel stroke, which is the primary risk factor for VD." (PMID 39415269, 2024). "Similarly, aside from a non-significant association with HF, these plasma CETP concentration analyses were able to replicate the associations with cardiovascular outcomes, and extended these to show a protective effect on small vessel stroke." (PMID 38906890, 2024). "We recapitulated and extended known beneficial effects of lower CETP levels on blood lipids, as well as protective effects on cardiovascular diseases such as CHD, AAA, HF, and small vessel stroke." (PMID 39415269, 2024).
vascular dementia (3 papers, 2024). A degenerative vascular disorder affecting the brain. "There is also little evidence to support an effect of CETP inhibition on all-cause or vascular dementia." (PMID 39702548, 2024).
abdominal aortic aneurysm (2 papers, 2021 to 2024). Enlargement and ballooning of the vessel that supplies arterial blood to the abdomen, pelvis and legs. "CETP variants, resulting in genetically proxied reduction in LDL-C levels, reduced the risks of aortic aneurysms (OR = 0.22, 95% CI = 0.10–0.48, p = 2 × 10−4) and abdominal aortic aneurysms (OR = 0.08, 95% CI = 0.03–0.24, p = 7 × 10−6)." (PMID 34834523, 2021).
acute coronary syndrome (2 papers, 2017 to 2024). Signs and symptoms related to acute ischemia of the myocardium secondary to coronary artery disease. "The findings of eight of the studies were pooled to assess the influence of CETP inhibitors on hospitalization due to acute coronary syndrome in comparison to a placebo group." (PMID 38786974, 2024).
acute kidney injury (2 papers, 2019 to 2021). Sudden and sustained deterioration of the kidney function characterized by decreased glomerular filtration rate, increased serum creatinine or oliguria. "CETP also affected the development of acute kidney injury in septic shock." (PMID 30736368, 2019). "CETP regulation of HDL-C levels during acute infection critically modulates mortality and acute kidney injury." (PMID 30736368, 2019).
aneurysm (2 papers, 2021 to 2022). Bulging or ballooning in an area of an artery secondary to arterial wall weakening. "The inverse correlation of CLC with ABCA1-CEC and CETP activity found only in AAA is again consistent with the existence of a link between accelerated HDL metabolism, intracellular cholesterol, and aneurysm formation." (PMID 36172376, 2022).
aortic atherosclerosis (2 papers, 2017 to 2025). A atherosclerosis that involves the aorta. "In our study, Tg rabbits with a higher CETP concentration had low levels of HDL-C and high levels of TGs but did not exhibit a significant effect on gross lesion area of aortic atherosclerosis." (PMID 29317793, 2017).
carotid atherosclerosis (2 papers, 2012 to 2021). A thickening and loss of elasticity of the walls of carotid arteries that occur with formation of atherosclerotic plaques. "The relation of one additional CETP SNP (rs12444708) with carotid atherosclerosis appears to be HDL-C-dependent, in that it was associated with a significant pro-atherosclerotic effect only in the presence of high HDL-C levels." (PMID 33799675, 2021). "The present study suggests the existence of a relationship between CETP and carotid atherosclerosis, as supported by the independent association of three CETP SNPs (rs34760410, rs12920974, rs12708968) with cIMTmax." (PMID 33799675, 2021). "Consistently, we found that, among subjects with high HDL-C, high CETP concentrations were associated with a burden of carotid atherosclerosis at least as high as that of subjects with low/medium HDL-C." (PMID 33799675, 2021). "This suggests that the association of HDL-C with carotid atherosclerosis is CETP-dependent." (PMID 33799675, 2021). "Conversely, the HDL-C impact on carotid atherosclerosis could be influenced by the CETP concentration." (PMID 33799675, 2021). "Accordingly, a relationship between CETP rs12444708 and carotid atherosclerosis influenced by HDL-C may be inferred." (PMID 33799675, 2021). "None of the studied parameters, including CETP activity, explained the different relationships between these polymorphisms and cIMT, suggesting that other non-determined factors were affected by the genotypes and related to carotid atherosclerotic disease." (PMID 23039379, 2012).
cholestasis (2 papers, 2020 to 2021). Impairment of the bile flow caused by obstruction within the liver, or outside the liver in the bile duct system. "CETP activity in humans is known to be influenced by high plasma cholesterol concentrations, or by cholestasis." (PMID 32450892, 2020). "The absence of apparent cholestasis in animals expressing human CETP suggests the cycling of bile acids through the enterohepatic system is not impaired and is not likely the cause of the elevated cholesterol levels in the livers of these animals." (PMID 33515552, 2021).
diabetic retinopathy (2 papers, 2019 to 2021). "This study investigated CETP gene variants to assess the risk of T2D and specific complications of diabetic kidney disease (DKD) and diabetic retinopathy." (PMID 31597401, 2019).
gallbladder cancer (2 papers, 2021). "During an extensive literature survey, we found two studies that established the connection of CETP rs708272 genotypes with the risk of gallbladder cancer as well as with the risk of pituitary adenoma, but none of these were related to CRC." (PMID 33805921, 2021). "Similarly, decreased CETP gene expression was found in gallbladder cancer tissue." (PMID 33805921, 2021).
hepatocellular carcinoma (2 papers, 2016 to 2025). A malignant tumor that arises from hepatocytes. "Pitavastatin repressed LXR activation in a rat hepatoma cell line, which was indirectly supported by our result in which the activation of LXR by T0901317 antagonized the pitavastatin-induced reduction in CETP levels in HepG2 cells." (PMID 26984517, 2016).
hyperlipemia (2 papers, 2011 to 2019). "In particular, induction of hyperlipemia in rats fed a hyperlipemic rich diet for 90 consecutive days was accompanied by a significant increase of ACAT and CETP, this effect being associated with a significant reduction of LCAT and PON1 compared to normolipemic animals." (PMID 31101130, 2019). "The relationship between CETP and postprandial hyperlipemia is still unclear." (PMID 21609439, 2011). "The effect of BPF in counteracting alteration of the lipemic serum and glycemic profile induced by diet-related hyperlipemia was accompanied by significant improvement of Lipid Transport Protein System as detected by measurements of ACAT, LCAT, CETP and PON1." (PMID 31101130, 2019).
insulinoma (2 papers, 2016 to 2023). "indicate that insulin analog initiation therapy activates lipid metabolism via up-regulating cholesteryl ester transfer protein (CETP) and can increase HDL levels.In patients with insulinoma, islet cells can continuously secrete a large amount of insulin, resulting in hypoglycemia." (PMID 37033225, 2023).